CIITA (class II major histocompatibility complex transactivator)
Diseases named in the same sentence as CIITA in open-access papers (continued):
Sharing a sentence is not in itself a finding about the gene and the disease.
primary effusion lymphoma (1 paper, 2012). A large B-cell lymphoma located in the body cavities, characterized by pleural, peritoneal, and pericardial fluid lymphomatous effusions and that is always associated with human herpes virus-8 (HHV-8). "Another herpes virus protein vIRF3 from KSHV, which is expressed in latently infected primary effusion lymphoma (PEL) cells also inhibits the transcription of CIITA and suppresses the expression of MHC-II molecules." (PMID 23012630, 2012).
rectal cancer (1 paper, 2022). A primary or metastatic malignant neoplasm that affects the rectum. "(G) CIITA expression in colon and rectal cancer cell lines with WT Fbw7 (n=47) and mutated Fbw7 (n=23)." (PMID 35225231, 2022).
Stroke (1 paper, 2014). Sudden impairment of blood flow to a part of the brain due to occlusion or rupture of an artery to the brain. "Our microarray analysis revealed that RHP suppresses B cell antigen presentation prior to stroke in protected mice via downregulation of the master transcriptional regulator CIITA and several downstream MHC I and MHC II receptors." (PMID 24485041, 2014).
T-cell ALL (1 paper, 2004). "In summary, we have shown that the aberrant methylation of CIITA-PIV is associated with the silencing of CIITA-PIV and HLA-DR expression in T-cell ALL." (PMID 14970863, 2004).
toxoplasmosis (1 paper, 2022). A parasitic disease contracted by the ingestion or fetal transmission of toxoplasma gondii. "In addition to the TNF pathway, we detected enrichment of candidate genes involved in the toxoplasmosis (TGFβ2/CHUK/CIITA/SOCS1) pathway in the tolerant animals." (PMID 35464478, 2022). "In addition, the TNF-signaling (bta04668; TRAF5/CREB5/CASP7/CHUK) and the toxoplasmosis (bta05145; TGFβ2/CHUK/CIITA/SOCS1) pathways were significantly enriched." (PMID 35464478, 2022).
ulcerative colitis (1 paper, 2019). An inflammatory bowel disease involving the mucosal surface of the large intestine and rectum. "In addition, a human GWAS study showed an association with variants at CIITA and levels of activated T cells (i.e., HLA DR+ T lymphocytes) and is in linkage disequilibrium with disease variants associated with ulcerative colitis." (PMID 31697674, 2019).
viral myocarditis (1 paper, 2022). Myocarditis that is caused by an infection with a viral agent. "However, CIITA knockout caused a significant decrease in a cluster of SLA-II molecules, involved in immune- and infection-relevant pathways, including antigen processing and presentation and viral myocarditis, and made these pigs susceptible to pathogenic microorganisms." (PMID 35573408, 2022).
tumor (124 papers, 2000 to 2026). "CIBERSORT deconvoluted CIITA-associated immune landscapes within the tumor immune microenvironment (TIME)." (PMID 40861816, 2025). "CIITA expression is decreased in several types of hematological and solid tumours and is associated with decreased tumour immune recognition." (PMID 26466379, 2015). "Our results suggest that DNA methylation of CIITA-PIV is also a major cause of HLA-DR suppression in haematopoietic tumour cells, especially those derived from T-cells and myeloid cells." (PMID 14970863, 2004). "CIITA mutations may disrupt its regulatory role in immune responses, leading to immune evasion and tumor progression." (PMID 40861816, 2025). "Furthermore, our bioinformatic deconvolution of the tumor immune contexture revealed that CIITA expression is associated with immune checkpoints and interferon-γ signalling, hallmarks of an active tumor-immune interface." (PMID 40861816, 2025). "Novel tumour-associated mutations in CIITA and MUC16 were recorded in the Indian cohort." (PMID 37091785, 2023). "Additionally, the CIITA prognostic results showed that its high expression in four tumor types was associated with a poor prognosis, and its low expression in eight tumor types was associated with a poor prognosis." (PMID 36555243, 2022). "Also a number of tumor cells, such as primary mediastinal large B Cell lymphomas, display CIITA mutations which result in diminished MHC II expression to allow immune escape of tumor cells." (PMID 28615693, 2017). "The rationale underlying this approach was that CIITA-transfected tumor cells may act as “surrogate APC” via MHC-II-restricted tumor-associated antigen presentation to tumor-specific TH cells for their optimal triggering." (PMID 22849661, 2012). "Both hypermethylation of the CIITA promoter IV and/or modification of chromatin structure by histone deacetylation may result in defective CIITA expression in tumor cells, causing a loss of INF-gamma-inducible HLA-DR expression." (PMID 24212778, 2011). "Our finding that CIITA is remarkably specific for genes implicated in antigen presentation is consistent with the hypothesis that the association between silencing of CIITA and tumorigenicity reflects a reduction in the antigen presentation capacity of the tumor cells." (PMID 18437201, 2008). "Previous work on carcinoma cell lines, and more recently on murine glioma cells, found that ectopic stable expression of CIITA transforms tumor cells into MHC‐II‐positive cells with enhanced antigen processing and presentation capabilities." (PMID 39535369, 2025). "Although bioinformatics and IHC support the prognostic value of CIITA, functional assays are needed to elucidate its direct role in tumor and stromal biology." (PMID 40861816, 2025). "To convert MHC‐II‐negative GB tumor cells into APC‐like cells, we generated a replication‐deficient AdV carrying the wild‐type CIITA gene (Ad‐CIITA) or a mutated CIITA transgene (Ad‐CIITA mutant)." (PMID 39535369, 2025). "Within oncological contexts, CIITA augments tumor cell recognition by the immune system through upregulation of MHC II surface molecules, thereby facilitating efficient antigen presentation to CD4+ T lymphocytes 11-13." (PMID 40861816, 2025). "MHC-II protein depletion completely abolished tumor reduction caused by RCOR2 loss in mice, which phenocopied CIITA loss." (PMID 40608411, 2025). "For example, in vivo studies have shown that transduction of tumor cells with ectopic HLA class II or CIITA increases CD4 + T cell and CD8 + T cell-mediated tumor rejection, implying that suppressing HLA class II expression is necessary for tumor progression." (PMID 39928678, 2025). "In an attempt to identify non‐classical T‐cell activation mechanisms, we investigated the secretion of cytokines upon tumor cell killing mediated by wild‐type CIITA at 72 h post‐co‐culture." (PMID 39535369, 2025).
tumor (continued). "We found that while Ad‐CIITA infection has limited impact on tumor cell growth, effective killing of infected GB organoids is activated and maintained only in the presence of immune cells." (PMID 39535369, 2025). "Nucleophosmin 1 (NPM1), a nucleolar phosphoprotein, suppresses tumour immunogenicity by binding to IRF1 and preventing its association with the NLRC5 and CIITA promoters." (PMID 40673641, 2025). "Upon addition of allogenic PBMCs, we observed a pronounced organoid disruption and tumor cell killing in Ad‐CIITA‐infected organoids (86.5% ± 10.2), contrasting with a lower effect in Ad‐null‐infected organoids (42.2% ± 7.3)." (PMID 39535369, 2025). "Similar results were seen in T16 and T188 organoids, where pronounced tumor cell death was induced by Ad‐CIITA and again, though to a lesser extent, by Ad‐CIITA mutant." (PMID 39535369, 2025). "In summary, our findings show that both Ad‐CIITA and Ad‐CIITA mutant enhance the immunogenicity of GB for allogenic T‐cells, facilitating efficient tumor cell killing in the presence of either CD4+ or CD8+ T‐cells." (PMID 39535369, 2025). "This relationship positions CIITA as both a promising prognostic indicator and a potential therapeutic target for modulating anti-tumor immunity." (PMID 40861816, 2025). "Beyond its established functions in adaptive immunity, CIITA demonstrates significant contributions to anti-tumor immunity." (PMID 40861816, 2025). "Ectopic CIITA/MHC-II expression reprograms tumor microenvironments by displacing immunosuppressive macrophages and neutrophils with activated CD4+/CD8+ T cells, bolstering antitumor immunity." (PMID 40861816, 2025). "Although CIITA is well recognized for its role in antigen presentation in immune cells, its function in tumor immunity and prognosis remains underexplored." (PMID 40861816, 2025). "The mechanism by which CIITA induces an MHC‐II‐independent immune‐mediated tumor cell death remains to be determined." (PMID 39535369, 2025). "After stimulated by IFNγ, tumor cells would express transcriptional regulator class II transactivator (CIITA), which induces the expression of MHC-II, through the JAK/STAT signaling pathway." (PMID 39105803, 2024). "NSG (immunodeficient) and nude (athymic) mice were injected in the striatum with GL261-wildtype (-WT) and -CIITA, and tumor growth was assessed by immunohistology and luminescence reporter genes." (PMID 39594630, 2024). "MHC-II expression in cells, including tumor cells, is under the control of the class II transactivator (CIITA), identified for the first time by our research group." (PMID 39035008, 2024). "Tumor subtype was an additional variable, with hepatocellular carcinoma having high expression and cholangiocarcinoma having low CIITA and B2M protein levels." (PMID 38915093, 2024). "Western blot analysis of nuclear and cytoplasm fractions indicated that the concentration of β-arrestin and CIITA in the nucleus was increased by about 50% in pDCs after CCL21 treatment or tumor cells co-culture." (PMID 39456552, 2024). "Comparison of the level of CIITA expression across all cancer cell clusters confirmed that CIITA was also significantly more lowly expressed in early WGD tumours (coeff." (PMID 39025846, 2024). "In preclinical experiments, the effects of CIITA on tumor growth should further be assessed prior to concluding on its potential for antitumor immune vaccination strategies." (PMID 39594630, 2024). "We demonstrate that CIITA-OSCC cells are potent stimulators of an adaptive immune response that protects the mouse from tumor onset or significantly retards tumor growth." (PMID 39035008, 2024). "Recently, we identified CD4+ T cell neo-epitopes of this tumor by peptide elution from MC-38 cells induced to express MHC class II by transfection with the MHC class II transactivator (CIITA) gene." (PMID 39040850, 2024).
tumor (continued). "A similar finding was previously observed by our group in mice rejecting GL261 tumor cells genetically modified to express MHC class II molecules after Class II Transactivator (CIITA) transfection." (PMID 39334370, 2024). "The study has shown that interferon-γ (IFN-γ) induces tumor cells to express MHCII through MHC class II transactivator (CIITA), which is recognized and killed by cytotoxic CD4 + T lymphocyte (CD4 + CTL)." (PMID 38816871, 2024). "In deep analysis of the mechanisms leading to tumor rejection demonstrated crucial aspects of the immune response induced by CIITA-expressing tumor cells." (PMID 37467968, 2023). "FoxP3 was upregulated in TIL after co-culture with CIITA-expressing syngeneic tumor cells (PGB1) as compared to co-cultures with the corresponding wildtype tumor cells (p = 0.04)." (PMID 38201622, 2023). "Expression of MHC-II in tumor cells can be restored by interferon gamma treatment or forced overexpression of CIITA, the major regulator of MHC-II." (PMID 38201622, 2023). "Given the limitations of our murine model, we assessed the effects of CIITA expression in tumor cells on human immune cells." (PMID 38201622, 2023). "Depending on its expression level, HDAC2 can positively or negatively control the transcriptional activity of CIITA and B2M, which, in turn, can be differently regulated within the tumor microenvironment." (PMID 37046620, 2023). "We explored tumor-infiltrating immune cells in COAD tumors from the TCGA cohort with different SCNAs in CIITA, HDAC2, and B2M." (PMID 37046620, 2023). "To assess the potential of splenocytes primed with CIITA-expressing GB cells to suppress the intracerebral tumor growth of wildtype GB cells, we performed adoptive cell transfer experiments." (PMID 38201622, 2023). "The same requirement of exogenous target peptide loading was observed with CIITA-transduced tumor cells (HNSCC-56 CIITA), which constitutively express high levels of surface MHC-II." (PMID 36512410, 2023). "First, immunity to CIITA-tumor cells was long lasting and capable to counteract the growth of parental CIITA-negative tumor cells." (PMID 37467968, 2023). "The idea was to modify tumor cells by transducing them with of CIITA and thus render them MHC-II-positive, closely mimicking the physiological expression of MHC-II molecules." (PMID 37467968, 2023). "In accordance with the elevated MHC class II heavy and light chain gene expression, CIITA expression was also significantly higher in HPV+ than HPV− tumor samples." (PMID 36497170, 2022). "Multivariate analysis controlling for tumour stage and age highlights CIITA and IKZF3 as candidate prognostic biomarkers." (PMID 35743743, 2022). "CIITA-Exo enhanced the splenocyte proliferation and IL-2 secretion, and induced inflammatory cytokines (such as TNF-α and IL-12) mRNA production, so that CIITA-Exo had a more potent anti-tumor immune response compared to control Exos." (PMID 36733388, 2022). "Within the tumor microenvironment, osteocytes interact with myeloma cells to promote the development of bone lesions through a complex pathway involving TP, 2DDR and CIITA." (PMID 35760800, 2022). "CIITA-overexpressing DFT cells can be exploited for enhancing tumour immunogenicity on a vaccine platform through increased antigen presentation via MHC-I and MHC-II molecules." (PMID 36259237, 2022). "The expression of MHC-II on CIITA-expressing DFT cells can offer insight into the importance of CD4+ T cells in the interplay with other immune cells for anti-tumour immunity and allograft rejection." (PMID 36259237, 2022). "The multivariate four-factor model (tumour stage, age, CIITA, IKZF3) was validated in the MEL_TCGA independent validation data (n = 135, TCGA_VALID)." (PMID 35743743, 2022). "A significant top-scoring model (tumour stage, age, CIITA, IKZF3, CD247, TENT5C; likelihood ratio test p = 2 × 10−7) was returned for the MEL_TCGA training set (n = 255, TCGA_TRAIN)." (PMID 35743743, 2022).
tumor (continued). "In mice models, CIITA expressing tumor cells can be efficiently rejected when injected into immunocompetent syngeneic mice." (PMID 33592498, 2021). "Considering this drawback, they conducted a in vivo in mice assay and found that CIITA-driven MHC class II expression in tumor cells revealed strong inhabitation of tumor growth." (PMID 34404901, 2021). "In fact, loss-of-function (LOF) alterations in NLRC5 and CIITA were consistent with the loss of MHC class I and class II expression in NPC tumor cells." (PMID 34234122, 2021). "In agreement with the decrease in MHC-II induced by tumor cells, after a five-day co-culture, the expression of CIITA was strongly decreased." (PMID 34680345, 2021). "Vaccination with CIITA-driven MHC-II-expressing tumor cells has a potential to induce a potent TH immune response through a diverse antigenic repertoire and to transform the tumor microenvironment from a noninflamed to an inflamed phenotype." (PMID 33592498, 2021). "Among them, CIITA has been shown to drive MHC Class II expressing tumor cells as professional antigen presenting cell (APC) performers, thus activating the immune cells and constructing the specific optimal anti-tumor vaccine." (PMID 33509250, 2021). "RNA-seq analysis from in vivo samples of these cell lines revealed that sensitivity to the therapy was dependent on the CIITA-mediated expression of tumor-cell-specific MHC-II." (PMID 33499042, 2021). "We concluded that CIITA-expressing tumor cells are attractive models for antigen discovery endeavors, especially in HLA-II negative tumors such as GBM." (PMID 33592498, 2021). "Preclinical vaccination research in vivo with tumor cells expressing CIITA led to an immune response against the CIITA-transfected tumor and, most importantly, against the parental tumor." (PMID 33592498, 2021). "Binding by RACK7 modifies the chromatin environment and suppresses the expression of CIITA, and thus limits the immunogenicity of the tumor." (PMID 33499042, 2021). "We further showed that transfecting CIITA into tumor cells raised their ability to in vivo prime naïve CD4+ cells, thus, they serve as APCs." (PMID 33592498, 2021). "One of the most prominent examples of cancers where CIITA inactivation participates in tumor proliferation is the primary mediastinal large B-cell lymphoma (PMLBCL)." (PMID 33499042, 2021). "Vaccination of mice with tumor cells expressing CIITA led to an immune response against the CIITA-transfected tumor and, most importantly, against the parental tumor." (PMID 33592498, 2021). "Is the adequate antigen availability to prime and stimulate naïve CD4+ Th cells generated by CIITA-driven MHC-II expressing tumor cells useful in clinical setting for novel strategies of anti-tumor therapy?" (PMID 33138029, 2020). "Taken together, these studies gave strong support to the real helper nature of CD4+ T cells in initiating and supporting the anti-tumor immune response, provided that they were triggered by CIITA-driven MHC-II+ tumor cells." (PMID 33138029, 2020). "Our approach is based on rendering the very same tumor cells antigen presenting cells for their own tumor antigens by gene transfer of CIITA, the major transcriptional coordinator of MHC class II expression discovered in our laboratory." (PMID 33138029, 2020). "The results clearly indicated that the depletion of either naive CD4+ or naïve CD8+ T cells, but not B cells or NK cells, abrogated the protection against live CIITA-tumor cells." (PMID 33138029, 2020). "The absolute requirement of CIITA-driven MHC-II positive tumor cells to trigger tumor-specific CD4+ Th cells and initiate the cascade of events, leading to an efficient adaptive anti-tumor immune response raised several key questions." (PMID 33138029, 2020). "Tumor mass formation rate within 18 days of the first injection of wild type (WT), B2M−/−, CIITA−/−, and B2M−/− and CIITA−/− were 2/7, 3/7, 4/7, and 6/7, respectively." (PMID 32746912, 2020).